CCL5 (C-C motif chemokine ligand 5)
Diseases named in the same sentence as CCL5 in open-access papers (continued):
Sharing a sentence is not in itself a finding about the gene and the disease.
liver fibrosis (continued). "NKT cells and CXCL and CCL signaling pathway such as Cxcl16-Cxcr6, Ccl6-Ccr2 and Ccl5-Ccr5 might be potential targets to alleviate hepatic fibrosis of schistosomiasis." (PMID 36618421, 2022). "Liver fibrosis has been reported to be exacerbated by Ccl5 secreted by HSCs22." (PMID 35194060, 2022). "There is growing evidence that CCR2/CCR5 and its ligands, including MCP-1 (CCL2) and RANTES (CCL5), are involved in the pathogenesis of liver fibrosis through the promotion of monocyte/macrophage mobilization and tissue infiltration, and the activation of HSCs after liver injury." (PMID 34938271, 2021). "Inhibition of CCL5 may accelerate the regression of liver fibrosis through inhibiting function of HSCs and balancing monocyte/macrophage subsets." (PMID 33623529, 2021). "A previous study suggested that CD8 T cells (Ccl5+, Ccl4+) might promote liver fibrosis via extrahepatic recruitment in response to liver injury." (PMID 33391261, 2020). "Mechanistically, the orphan nuclear receptor RAR-related orphan receptor alpha (RORα) activates the expression of the liver fibrosis-related chemokines C-C motif chemokine ligand 5 (CCL5) and C-X-C motif chemokine ligand 10 (CXCL10), which is suppressed by the Mediator subunit MED23." (PMID 31805036, 2019). "Of interest, chemokine genes, such as CCL5, CCL2 and CXCL10, could activate human hepatic stellate cells, which are associated with hepatic fibrosis, and CXCL10 is an important gene for the treatment response of interferon treatment." (PMID 26133378, 2015). "CCL5 is a chemokine produced by monocyte/macrophage subsets in the liver, which contributes to recruiting T cells and other leukocytes to the infection site and also to the progression and resolution of liver fibrosis." (PMID 25111807, 2014). "While the role of CCL5 as a fibrotic mediator is less clear compared to that of CCL2, there is some evidence that antagonism of CCL5 may be therapeutic in liver fibrosis, possibly through the modulation of monocyte subpopulations." (PMID 24478701, 2013). "Furthermore, antagonism of the CCL5 receptors with Met-CCL5 ameliorated liver fibrosis and accelerated the regression of scar formation in vivo." (PMID 22574195, 2012). "Moreover, RANTES/CCL5 is also involved in the progression of hepatic fibrosis in mice." (PMID 28420094, 2017). "In the progress of liver fibrosis, peripheral pro-inflammatory mononuclear MoMφs can be attracted to the liver depending on CCL2/CCR2, CCL5/CCR5, and CCL1/CCR8 chemokines axis and aggravate liver fibrosis." (PMID 39635524, 2024). "A series of studies have shown that CXCL9, IL15 and CCL5 up-regulated significantly in hepatocytes of HCV-infected patients and MASH patients, and existed a correlation between CXCL9 levels and liver fibrosis." (PMID 39605886, 2024). "Kupffer cells play a role from the early stages of liver fibrosis; they sense the disruption of liver homeostasis and subsequently express chemokines such as CCL2 and CCL5." (PMID 39629085, 2024). "For example, the chemokine CCL5 was found to trigger migration of TWNT-4 stellate cells and to be involved in the development of experimental liver fibrosis." (PMID 35625625, 2022). "The post-interventional dynamics of physiologically relevant adipokines and hepatokines (ANGPTL4, CCL5, GDF15, GPNMB, IGFBP6), as well as their correlation with fat mass reduction and improvement of liver fibrosis, were analyzed." (PMID 36430499, 2022). "Among these hub genes, some are cytokines and chemokines closely related to liver fibrosis (IFNG, CCL3, CCL4, CCL5, and CXCR4)." (PMID 35903097, 2022). "In contrast, blocking antibodies against CCL5 inhibited HSCs activation and HCV-related liver fibrosis." (PMID 35707547, 2022). "An antagonist of CCL5 was found to ameliorate liver fibrosis and prevent HCC in mouse models, which further strengthened the relationship between CCL5 and liver fibrosis or carcinogenesis." (PMID 34041839, 2021).
liver fibrosis (continued). "The CCL5 expression level in serum increased in CHB patients with aggravated liver injury and significantly decreased in cirrhosis patients with advanced liver fibrosis." (PMID 31200663, 2019). "After having shown that treatment with [44AANA47]-CCL5 has a strong impact on the extent of acute inflammatory liver damage, we next evaluated whether this antagonistic strategy does also inhibit progression of liver fibrosis induced by repetitive CCl4 intoxications." (PMID 22574195, 2012). "Hence, the inhibition of CCL2/CCR2, CCL5/CCR5, and CCL1/CCR8 chemotaxis shows potential efficacy to repair liver fibrosis." (PMID 39635524, 2024). "While gene expression of inflammatory markers Ccl5 and Tnfα remained unchanged among the groups, hepatic hydroxyproline content as well as PSR (as a marker of hepatic fibrosis)-positive areas were reduced in liver sections of cilofexor-treated Mdr2-/- mice in comparison to Mdr2-/- control animals." (PMID 37841639, 2023). "Our study demonstrated that hepatic RORα, in cooperation with MED23, plays a role in inflammatory responses, acting as a positive regulator of CCL5 and CXCL10 in initiating the liver fibrosis, which suggests new molecular targets for clinical intervention in liver fibrosis." (PMID 31805036, 2019). "Antagonizing the interaction of CCL5 and its receptor CCR5 with Met-CCL5 could obviously ameliorate the progression of hepatic fibrosis and promote the regression of hepatic fibrosis." (PMID 31200663, 2019). "Inflammatory macrophages, which promote inflammation and liver fibrosis, are activated by Toll-like receptors (TLR), with release of inflammatory (TNF, IL-1β) and pro-fibrogenic mediators (TGF-β and Gal-3) as well as chemokines (MCP-1, CCL5)." (PMID 31015492, 2019). "Although Ccl5 is a relatively well-investigated chemokine, known to promote hepatic fibrosis, its possible pro-steatotic effect has not been investigated." (PMID 29760499, 2018). "Importantly, administration of mice with Met-CCL5, a CCR1/CCR5 antagonist, attenuated liver fibrosis and accelerated the regression of fibrosis during follow-up." (PMID 23799074, 2013). "Moreover, CCR1 and CCR5, receptors for the chemokines CCL3/MIP1α, CCL4/MIP1β and CCL5/RANTES, were found to promote liver fibrosis in mice." (PMID 23259611, 2012). "Moreover, CCR1 and CCR5, receptors for the chemokines CCL3/MIP1α, CCL4/MIP1β and CCL5/RANTES, promote liver fibrosis in mice." (PMID 20548789, 2010). "In this study, we showed that lnc-Lfar1 silencing alleviated liver injury-induced upregulation of LY6C, IL-1β, IL-6, TNF-α, MCP-1, CCL5 and CXCL10 in vivo and in vitro, suggesting that lnc-Lfar1 knockdown might be beneficial for preventing liver fibrosis by targeting these chemokines." (PMID 32071306, 2020). "This strongly predictive character for hepatic fibrosis was exclusively observed for GDF15 but not for ANGPTL4, CCL5, GPNMB, and IGFBP6." (PMID 36430499, 2022).
hepatocellular carcinoma (55 papers, 2007 to 2026). A malignant tumor that arises from hepatocytes. "The promotion of hepatocellular carcinoma metastasis was also facilitated by the activation of the HIF1α/ZEB1 axis through CCL5 derived from cancer‐associated fibroblasts." (PMID 40062588, 2025). "Two chemokines, chemokine ligand 2 (CCL2) and CCL5, play major roles in the accumulation of tumor-associated macrophages (TAMs) and induction of immunosuppression in hepatocellular carcinoma (HCC)." (PMID 36839944, 2023). "CXCL10 is an IFN-γ induced protein and alterations in its expression have been associated with inflammatory milieu and infectious diseases, whereas CCL5 has been reportedly associated with a crucial role in hepatocellular carcinoma development in murine and human models." (PMID 32784775, 2020). "Cancer-associated fibroblasts-derived CCL5 is responsible for the progression of hepatocellular carcinoma (HCC) and cancer cell metastasis." (PMID 40863244, 2025). "For instance, the chemokine CCL5, produced by CAFs, promotes Hepatocellular carcinoma (HCC) metastasis by activating the HIF1/ZEB1 axis." (PMID 38445456, 2024). "Conversely, educated MSCs secrete CCL5 to facilitate macrophage recruitment and establish a chronic inflammatory microenvironment that drives the occurrence of hepatocellular carcinoma (HCC)." (PMID 38779660, 2024). "Pyroptotic macrophages can increase the cytotoxicity of NK cells in hepatocellular carcinoma by producing CCL5 and IL-18 and thus kill more tumor cells." (PMID 35656090, 2022). "Our study also observed a lower level of CCL5 in the serum of patients with cirrhosis, and CCL5 expression in serum of patients increased significantly in the development from cirrhosis to hepatocellular carcinoma." (PMID 35589690, 2022). "Chemokines secreted by hepatoma cells, such as CCL5, CCL22, and CCL28, increase the infiltration of those Tregs, leading to the impaired activity of antigen-presenting cells (APCs) and immune cells in TME." (PMID 35965575, 2022). "SDC4 is essential in RANTES/CCL5-mediated hepatoma cell invasion and migration and its binding to the cell plasma membrane." (PMID 34282767, 2021). "For example, syndecan-4 affects hepatoma and HeLa cell motility and invasion by facilitating signaling via chemokines such as RANTES/CCL5 and SDF-1, which is in accordance with the role of heparan sulfate in chemokine signaling." (PMID 33810567, 2021). "SDC4 is also involved in the RANTES/CCL5 signaling and is necessary in RANTES/CCL5-induced invasion and migration of hepatoma cell lines." (PMID 34282767, 2021). "In contrast, CCL5 was strongly reduced in human hepatoma cells, with the opposite response in TAA‐treated mice." (PMID 32821877, 2020). "CCL5 could recruit M2 macrophages and increase the ratio of M2/M1 in the progression of hepatocellular carcinoma and osteogenesis." (PMID 36713454, 2022). "It is also involved in RANTES/CCL5-induced migration and invasion of human hepatoma cells." (PMID 33810567, 2021). "The chemokine CCL5/RANTES (regulated upon activation normal T cell expressed and presumably secreted) contributes to the progression of injury during chronic liver disease, and leads to hepatocellular carcinoma (HCC)." (PMID 34889885, 2021). "The synthetic polymers OTR4120 or OTR4131 were shown to directly bind the proinflammatory basic chemokine CCL5 (regulated on activation, normal T cell expressed and secreted; RANTES) and to inhibit the the CC-chemokine-stimulated migration and invasion of the human hepatoma cell line HuH7." (PMID 30413079, 2018). "Circ_0003410 promotes hepatocellular carcinoma (HCC) proliferation and migration by sponging miR‐139‐3p and upregulating CCL5 expression." (PMID 40356340, 2025). "In hepatocellular carcinoma (HCC) tissues, CAFs secrete CCL2 and CCL5 and induce metastasis by activating the hedgehog pathway." (PMID 34445235, 2021).
hepatocellular carcinoma (continued). "Other investigators reported a dominating role of CCL3, CCL5 and CX3CL1 but not CCL2 in the migration of M-MDSC or an importance of CXCL-1 (also known as KC), CCL5 and CCL7 in the MDSC enrichment in mouse colon and liver carcinoma models." (PMID 27827871, 2016). "We then performed bulk RNA sequencing (RNAseq) on CCL5‐stimulated Huh7 cells and discovered the CCL5/CCR5/CYP1A1 pathway, which may prompt the drug resistance of hepatoma cells to lenvatinib." (PMID 39183447, 2024). "In hepatocellular carcinoma, CAF-derived CCL5 (also known as RANTES) promotes metastasis by binding to a specific receptor, CCR5, and inhibiting the ubiquitination and degradation of HIF-1α, maintaining HIF-1α even under normoxia, thereby upregulating the downstream gene ZEB1 and inducing EMT." (PMID 36831453, 2023). "Three specific receptors of CCL5 include CCR1, CCR3, and CCR5.We also found that CAF-derived CCL5 or exogenous hCCL5 could obviously enhanced the expression of CCR3 and CCR5 in hepatocellular carcinoma cells." (PMID 35589690, 2022). "Bone marrow stromal cell-derived C-C motif chemokine 5 (CCL5), also known as the chemotactic cytokine RANTES, was shown to induce migration and invasion of hepatocellular carcinoma cells via the PI3K/AKT pathway and, therefore, could promote bone metastasis." (PMID 34064589, 2021). "To investigate the role of CCL5 in CTC survival and the formation of metastases via Treg recruitment in vivo, we injected 5 × 106 Hepa1–6 murine hepatoma cells with or without knockdown of CCL5 into the tail veins of immune-competent C57BL/6J mice." (PMID 34215748, 2021). "Chronic hypoxia also does not affect CCL5/RANTES expression in hepatocellular carcinoma models, lung adenocarcinoma cells, and uveal melanoma cells." (PMID 32781743, 2020). "The results showed higher expression (p < 0.001) of CCR5 and CCL5 in hepatocellular carcinoma (HCC) tissues compared to non-neoplastic liver tissues." (PMID 32260550, 2020). "In addition, DENV infection of mouse hepatoma cell line, Hepa1–6, induced the expressions of CXCL10 and CCL5 mRNA." (PMID 23050007, 2012). "Hepatocellular carcinoma (HCC) tissue possessed a stronger metabolic reprogramming capacity for lenvatinib compared with liver tissue during the combination theapy based on anti‐PD1 antibody plus lenvatinib, as reflected by the activation of the CCL5/CCR5/CYP1A1 pathway." (PMID 39183447, 2024). "Relationships of serum C‐C motif chemokine ligand 5 (CCL5) and C‐X‐C motif chemokine ligand 10 (CXCL10) levels with hot immune features have been reported in patients with hepatocellular carcinoma (HCC)." (PMID 38133557, 2023). "CCL5 activity is mediated through its binding to CCR5, CCR3, and CCR1 but only CCR1 is expressed in hepatocellular carcinoma cells (HCC)." (PMID 35399952, 2022). "Importantly, CCL2, CCL5, and CXCL10 have been described in the process of conversion of senescent premalignant cells mediated by oncogenes activation that could culminate with hepatocellular carcinoma." (PMID 32784775, 2020). "Furthermore, in cases of hepatocellular carcinoma (HCC), tumor cells harness the CCL4/CCL5 chemokine pathway, interacting with the CCR1/CCR5 receptors, thereby orchestrating the mobilization of γδ T cells either from the peripheral blood or peritumor region to the tumor region." (PMID 38077392, 2023). "Strikingly, the main features were the lack of CCL5+ B-cells in HS and the presence of SESN1+ B cells in HS with hepatocellular carcinoma (HS-HCC)." (PMID 35865544, 2022).
influenza (54 papers, 2009 to 2025). An acute viral infection of the respiratory tract, occurring in isolated cases, in epidemics, or in pandemics; it is caused by serologically different strains of viruses (influenzaviruses) designated A, B, and C, has a 3-day incubation period, and usually lasts for 3 to 10 days. "RANTES recruits lymphocytes and NK cells to sites of inflammation, and in an influenza mice model deficient in RANTES/CCL5, delayed viral clearance and excessive inflammation occurred." (PMID 23284941, 2012). "We noted increased expression of genes related to cytotoxicity, activation and inflammation—such as GZMB, GNLY, TYROBP, HOPX, and CCL5—in the CD8 EMRA-like two cluster that was expanded in CAP-flu." (PMID 34424199, 2021). "Chemokine receptor 5 (CCR5) and its cognate chemokines CCL3, CCL4 and CCL5 are rapidly induced upon influenza infection, contributing to leukocyte recruitment into the airways and a consequent effective antiviral response." (PMID 35126379, 2021). "Because CCL5 showed, in conjunction, the best results for influenza inhibition and SAMHD1 enhancement levels, we selected this β-chemokine to continue the study." (PMID 34490131, 2021). "By day 7, expression of Ccl3, Cxcl9, Cd86, Il-6, Cd80, and Cxcl11 remained elevated in young adult lung in response to H1N1, while expression of Ccl5, Ccl4, and Cd40 remained elevated in response to either strain of influenza." (PMID 34829979, 2021). "Among these, indirubin has been shown to have potent anti-influenza viral activity via inhibition of RANTES (also known as CCL5) expression." (PMID 28085062, 2017). "Influenza-infected tissues release β-chemokines, such as CCL5 (Rantes), which is chemotactic for blood monocytes." (PMID 24978204, 2014). "Virus-infected cell clearance is impaired in influenza infected mice lacking CCL5 or by blocking CCL5 during respiratory syncytial virus infection, causing further tissue damage and a pro-inflammatory response." (PMID 38932231, 2024). "The available data suggests that, while CCL5 can play a protective role in influenza infection, CCL3 may contribute to an overwhelming inflammatory process that can harm the lung tissue." (PMID 35126379, 2021). "In addition, CCR5:CCL5 was shown to prevent virus-induced apoptosis of human and mouse macrophages during influenza infection." (PMID 35126379, 2021). "In vitro infection of type 2 human alveolar epithelial cells (hAECII) with either H1N1 or H5N1 virus leads to a significant production of CCL5 by those cells, showing that they may be a principal source of CCL5 during influenza pneumonia." (PMID 35126379, 2021). "Increased CCL5/RANTES level was noted during the recovery phase of influenza infections." (PMID 22022504, 2011). "Currently, the information obtained by the use of animal models suggests that while some CCR5 ligands, like CCL5, can play a protective role in influenza infection others, like CCL3, may contribute to an overwhelming inflammatory process which can harm the lung tissue." (PMID 35126379, 2021). "Whether CCR5 signaling in vivo directly regulates neutrophil activation or recruitment during influenza is yet to be explored; nevertheless, CCL5:CCR5 was shown to promote reprogramming of murine macrophages to pro-resolving phenotypes contributing to resolution of inflammation." (PMID 35126379, 2021). "The production of several chemokines involved in influenza severity, including CCL2/MCP-1, CCL3/MIP-1α, CCL4/MIP-1β, CCL5/RANTES, CXCL2/MIP-2, and CXCL10/IP-10 was also quantified." (PMID 40612502, 2025). "CCL5 and CXCL10 have previously been identified to be important in the recruitment of Trm to the lungs in an influenza model." (PMID 39749186, 2024). "In response to influenza viral entry, epithelial cells induce proinflammatory cytokines and chemokines such as IL-1β, IL-6, TNFα, CCL2, CCL3, and CCL5, which recruit macrophages and neutrophils to the site of infection to help control the virus." (PMID 38112660, 2023).